EYA1 (EYA transcriptional coactivator and phosphatase 1)
Diseases named in the same sentence as EYA1 in open-access papers (continued):
Sharing a sentence is not in itself a finding about the gene and the disease.
hearing loss (13 papers, 2009 to 2024). "and (EYA1_i003): p.(Arg106Ter) being found in isolated CLP cases on prenatal ultrasound, ARHGAP29 was more commonly associated with NSCL/CP, while EYA1 could cause hearing impairment or kidney abnormalities (OMIM #602588)." (PMID 37745857, 2023). "This may provide evidence for the progression of hearing loss demonstrated in some of the patients with EYA1 mutations considering the possible role of EYA1 in the maintenance and survival of the hair cells and the supporting cells." (PMID 23840632, 2013). "In terms of the clinical features of all BO/BOR-affected patients with EYA1 and SIX1 gene variants (19 probands and their family members who carried the same variants; 34 patients in total), the most frequent symptom was hearing loss (31/ 32, 97%)." (PMID 31427586, 2019). "There was a lower incidence of major and minor criteria, except hearing loss, among individuals with SIX1 variants compared to clinical EYA1 variant cohorts, and the phenotypic features related to DFNA23 or atypical BO syndrome were highlighted in SIX1 variants." (PMID 37479820, 2023). "In GER (CD−M3), Tecta, Pcdh15, and Cdc14a were associated with NSHL, Slitrk6 with deafness and myopia, Pcdh15 with Usher syndrome, Eya1 with branchiootorenal syndrome, Chd7 with CHARGE syndrome, and Cdc14a with hearing impairment and infertile male syndrome." (PMID 39684410, 2024). "In this study, no EYA1, MYO7A, or POU3F4 gene mutations were detected in any of the 717 hearing loss patients." (PMID 27627659, 2016).
deafness (11 papers, 2011 to 2024). An inherited or acquired condition characterized by the complete loss of the ability to hear from one or both ears. "In particular, mutations in developmental genes are associated with human deafness: for example Six1 or Eya1 mutations are known to cause Branchio-Oto-Renal Syndrome, an autosomal dominant disorder." (PMID 28264836, 2017). "This case suggests the opportunity of timely researching mutations of EYA1 gene in patient affected by deafness associated with urinary anomalies and/or branchial cysts or fistulae." (PMID 23506628, 2013). "In a sporadic deaf patient diagnosed as BOS, we identified an apparent heterozygous genomic deletion spanning the first four coding exons and one 5′ noncoding exon of EYA1 by targeted next-generation sequencing of 406 known deafness genes." (PMID 33880118, 2021). "The variants of TMC1, ESPN, POU3F4, MYH14, EYA1, and MR-RNR1 genes followed those from the top tier deafness genes in the order of frequency as a molecular etiology of severe-to-profound NSHL in Vietnamese." (PMID 30733538, 2019). "Mutations in nine deafness genes (COCH, KCNQ4, MYO7A, TECTA, CRYM, POU3F4, EYA1, mitochondrial tRNA(Lys) m.8296A>G, mitochondrial tRNA(Ser) m.7445A>G) were not identified in any patients." (PMID 22384008, 2012). "During inner ear development, many genes causing IEM and deafness have been identified, including SLC26A4, EYA1, FGFR3, and TCOF1." (PMID 21961810, 2011). "TECTA, WFS-1, MYH9, EYA1, COL4A5, COL11A1 were identified as the responsible genes for deafness in autosomal dominant families." (PMID 23967202, 2013). "TMPRSS3, MYO15A, GJB2, SLC26A4 were found to be responsible for deafness in autosomal recessive or sporadic families, while TECTA, WFS1, MYH9, EYA1, COL4A5 and COL11A1 were identified as the responsible genes for deafness in autosomal dominant families." (PMID 23967202, 2013).
branchio-oto-renal syndrome (10 papers, 2013 to 2025). "Mutations in eya1 cause branchio-oto-renal syndrome (BOR) in humans and the equivalent condition in animal models." (PMID 39381636, 2024). "Loss-of-function mutations in EYA1 leads to branchio-oto-renal syndrome, further suggesting that the gene is important for normal cellular function." (PMID 30013081, 2018). "EYA1 encodes a transcription factor where mutations have been associated with the branchio-oto-renal syndrome and other developmental abnormalities." (PMID 23496902, 2013). "Some of these are included in complex clinical syndromes such as branchio-oto-renal syndrome (EYA1, SIX1), renal-coloboma syndrome (PAX2), renal cysts and diabetes syndrome (TCF2/HNF1B) and Townes–Brocks syndrome (SALL1)." (PMID 28647851, 2018).
thyroid cancer (5 papers, 2019 to 2023). "Based on these data, high expressions of SIX1 and EYA1 are closely correlated with thyroid malignant tumor." (PMID 31921695, 2019). "Since PTC is the most common type of thyroid carcinoma and also occupied the majority of the tissue microarrays in this study, we next examined the association of SIX1 and EYA1 expression with clinicopathological parameters." (PMID 31921695, 2019). "Mutations in EYA1 may cause dysregulation and act as a tumor promoter with SIX1 via activation of STAT3 signaling in thyroid carcinomas." (PMID 38067373, 2023). "More importantly, EYA1 has been reported to drive thyroid carcinoma progression." (PMID 34773364, 2021). "However, the functional relationship of SIX1 and EYA1 in thyroid cancer remains to be discovered." (PMID 31921695, 2019). "Importantly, SIX1 strongly correlated with EYA1 in thyroid carcinoma tissue microarray." (PMID 31921695, 2019). "SIX1, a tumor promoter, promoted the proliferation and invasion of thyroid carcinoma via activation of STAT3 signaling and its downstream targets in an EYA1‐dependent manner." (PMID 32851683, 2020). "Since SIX1 is a DNA-specific transcriptional factor, whereas EYA1 basically acts as a co-factor to increase SIX1-dependent function, we mainly focused on the functional role of SIX1 in thyroid cancer for first." (PMID 31921695, 2019). "In this study, thyroid carcinoma tissue microarray staining was employed to identify the expression patterns of SIX1 and its co-activator EYA1." (PMID 31921695, 2019). "Besides, SIX1 promoted the proliferation and invasion of thyroid carcinoma via activation of STAT3 signaling and its downstream targets in an EYA1-dependent manner." (PMID 31921695, 2019).
branchiootic syndrome 1 (4 papers, 2021 to 2024). Any branchiootic syndrome in which the cause of the disease is a mutation in the EYA1 gene. "Branchiootic syndrome 1 (OMIM #602588) caused by EYA1 variants showed a variable spectrum of manifestations, including hearing loss, branchial fistulae, preauricular pits, and renal abnormalities." (PMID 35761346, 2022). "EYA1 is associated with Branchiootic syndrome 1 (OMIM: 602588)." (PMID 39767564, 2024).
congenital cataracts (4 papers, 2008 to 2023). "Mutations in the human EYA1 gene have been associated with several human diseases including branchio-oto (BO) and branchio-oto-renal (BOR) syndrome, as well as congenital cataracts and ocular anterior segment anomalies." (PMID 24489909, 2014). "Most genes are associated with isolated congenital cataracts while mutations in the transcription factor genes PAX6, FOXE3, EYA1, MAF, and PITX3 lead to congenital cataract with ASD." (PMID 24555714, 2014). "Neither Eya1+/- nor Eya1-/- mice reveal ocular defects and only in a few cases could Eya1 mutations be associated with congenital cataracts and ocular anterior segment anomalies in humans." (PMID 19102749, 2008).
renal agenesis (4 papers, 2011 to 2022). Renal agenesis (RA) is a form of renal tract malformation characterized by the complete absence of development of one or both kidneys (unilateral RA or bilateral RA respectively), accompanied by absent ureter(s). "Mutations in EYA1, PAX2, SIX1, or SIX2, have been found in a subset of human patients with renal agenesis or hypoplasia." (PMID 27442016, 2016). "Mice lacking the Eya1 exhibit renal agenesis due to lack of MM formation, while Eya1 deletion after UB outgrowth results in downregulation of Six2 expression and depletion and premature differentiation of the NPCs." (PMID 36130284, 2022). "The Eya1, Pax2, and Six1 transcription factors are each required for activation and/or maintenance of Gdnf expression in the metanephric mesenchyme and mice lacking any one of them die perinatally with bilateral renal agenesis." (PMID 27442016, 2016).
Wilms tumor (4 papers, 2012 to 2023). An embryonal neoplasm characterized by the presence of epithelial, mesenchymal, and blastema components. "EYA1 is overexpressed in Wilms’ tumors, EYA2 is overexpressed in epithelial ovarian cancers and lung carcinoma, and EYA4 overexpression has been detected in MPNST (malignant peripheral nerve sheath tumor)." (PMID 29340020, 2017). "Similarly, miR-562 contains an indel, the 18 bp deletion rs140596642, removing a large portion of the miRNA including the seed region, which may play a critical role in the development of Wilms’ tumor by both causing increased expression of miR-562 and dysregulation of its targets including EYA1." (PMID 23049969, 2012).
papillary thyroid carcinoma (3 papers, 2019 to 2023). "Association between SIX1/EYA1 expression and clinicopathologic factors in papillary carcinoma (TH8010 + TH802a)." (PMID 31921695, 2019). "In papillary thyroid carcinoma, high expressions of SIX1 and EYA1 were associated with advanced age, lymph node metastasis and clinical stage." (PMID 31921695, 2019). "Our study indicated that SIX1 and EYA1 might be used as malignancy hallmarks in papillary thyroid cancer." (PMID 31921695, 2019). "In papillary thyroid cancer tissues, protein expressions of SIX1 and EYA1 are positively correlated, SIX1 stabilizes EYA1 at the post-transcriptional level and activates STAT3 signaling requiring EYA1." (PMID 36750914, 2023).
amblyopia (2 papers, 2019 to 2022). Decreased vision that results from abnormal visual development. "The frequency of amblyopia is reported to be 3.0% to 3.2% in the general population, but the frequency of visual symptoms in the EYA1-related BO/BOR patients in this study was a little higher (9%)." (PMID 31427586, 2019).
BO syndrome (2 papers, 2022 to 2024). "Genetic testing identified a monoallelic pathogenic variant in EYA1 (c.1286A > G; p.Asp429Gly) segregating with BO syndrome in the family." (PMID 35698919, 2022). "Here, we report the first confirmed case of BO syndrome caused by a heterozygous pathogenic missense variant in EYA1 (c.1286A > G; p.Asp429Gly) in a large Malian family." (PMID 35698919, 2022). "This is the first genetically confirmed case of BO syndrome caused by EYA1 variant in the sub‐Saharan African population, expanding the genetic spectrum of the condition." (PMID 35698919, 2022). "We identified a monoallelic variant in the EYA1 gene in a Malian family with BO syndrome." (PMID 35698919, 2022). "Mutations in EYA1 are the most common causes of BOR/BO syndrome, and more than 200 pathogenic variants have been identified in various populations." (PMID 35698919, 2022). "To date, three genes (EYA1, SIX1, and SIX5) have been implicated in BO syndrome." (PMID 35698919, 2022). "There are three genes (EYA1; OMIM# 601653; SIX1; OMIM# 601205, and SIX5; OMIM# 600963) that are known to cause BOR/BO syndrome." (PMID 35698919, 2022).
breast tumor (2 papers, 2013 to 2023). "Somatic deletions in EYA1 were previously reported in four ER + breast tumors and one TNBC, revealing a combined prevalence of 7% (6 affected cases in a total of 85 samples investigated)." (PMID 23496902, 2013).
CHARGE syndrome (2 papers, 2020 to 2024). CHARGE syndrome is a multiple congenital anomaly syndrome characterized by the variable combination of multiple anomalies, mainly Coloboma; Choanal atresia/stenosis; Cranial nerve dysfunction; Characteristic ear anomalies (known as the major 4 C's). "Several neural crest regulatory molecules are known to cause ear/kidney syndromes with variable expression of both ear and kidney phenotypes (e.g., EYA1, SIX1, SIX5, CHD7, MASP1, TBX1), involved in BOR/BO syndrome, CHARGE syndrome, 3MC syndrome and DiGeorge syndrome." (PMID 32585897, 2020).
glioma (2 papers, 2015 to 2025). A benign or malignant brain and spinal cord tumor that arises from glial cells (astrocytes, oligodendrocytes, ependymal cells). "To determine substrates of EYA1 threonine phosphatase in glioma, we stably overexpressed EYA1 in U87MG cells and conducted phosphoproteomic analysis." (PMID 39897043, 2025). "In line with previous reports, we also find that EYA1 inhibition suppresses glioma cell growth in vitro and in vivo." (PMID 39897043, 2025). "Taken together, our data is consistent with the previous reports that EYA1 is essential for glioma cell growth in vitro and tumor formation in vivo." (PMID 39897043, 2025). "In our study, enforced EYA1 expression increases BCL2L12 expression in glioma cells, and, conversely, silencing EYA1 results in downregulation of BCL2L12." (PMID 39897043, 2025). "Disruption of the EYA1-BCL2L12 signaling pathway effectively inhibits glioma formation and progression, implicating EYA1 as a potential therapeutic target for glioma treatment." (PMID 39897043, 2025). "Our results indicate that BCL2L12 partially mediates the oncogenic roles of EYA1 in promoting glioma cell proliferation, highlighting the significance of EYA1's dephosphorylation of BCL2L12 in tumor progression." (PMID 39897043, 2025). "Collectively, these findings indicate that BCL2L12 partially mediates the oncogenic effects of EYA1 on glioma cell proliferation." (PMID 39897043, 2025). "To assess the impact of EYA1 on glioma tumor formation in vivo, we used the luciferase-expressing mouse glioma cell line GL261 for tumor transplantation assays." (PMID 39897043, 2025). "Taken together, these results suggest that EYA1-mediated dephosphorylation of BCL2L12 at T33 plays a crucial role in glioma tumor formation." (PMID 39897043, 2025). "In this study, we employed an unbiased phosphoproteomic approach and identified the essential glioma oncoprotein BCL2L12 as a novel substrate of EYA1 in glioma cells." (PMID 39897043, 2025). "In summary, this study identifies BCL2L12 as a new substrate for EYA1 threonine phosphatase activity in glioma development." (PMID 39897043, 2025). "In this study, we identify BCL2L12 (BCL2-like 12), a critical oncoprotein in glioma, as a novel substrate of EYA1 phosphatase in glioma cells." (PMID 39897043, 2025). "Using unbiased phosphoproteomics combined with a novel screening strategy, we identify BCL2L12 as an EYA1 threonine phosphatase substrate in glioma cells." (PMID 39897043, 2025). "In glioma cells, silencing EYA1 impaired cell proliferation, clonogenicity ability, and tumorsphere formation." (PMID 39897043, 2025). "In glioma patient samples, EYA1 was predominantly found in the nucleus, whereas BCL2L12 was mainly nuclear but also weakly detectable in the cytoplasm." (PMID 39897043, 2025). "We first evaluated the effects of EYA1 on BCL2L12 expression in glioma cells." (PMID 39897043, 2025). "We found that, besides the well-established c-Myc, only BCL2L12 met both criteria in our phosphoproteome data, suggesting that BCL2L12 might be a potential EYA1 substrate in glioma cells." (PMID 39897043, 2025). "Additionally, we show that BCL2L12 partially mediates the oncogenic function of EYA1 in glioma cells in a dephosphorylation-dependent manner." (PMID 39897043, 2025). "To distinguish whether BCL2L12 is regulated by the proteasome or lysosome mediated degradation pathways, we conducted rescue experiments in EYA1 knockdown glioma cells using the proteasome inhibitor MG132 and the lysosome inhibitor chloroquine (CQ)." (PMID 39897043, 2025). "We demonstrate that BCL2L12 interacts and colocalizes with EYA1 in glioma cells." (PMID 39897043, 2025). "Building on this finding, we screened for potential substrates of EYA1 in glioma cells using two criteria: the presence of the conserved “TPXXSP” motif; and the threonine phosphorylation level in this motif should be decreased in response to EYA1 overexpression." (PMID 39897043, 2025).
glioma (continued). "We then asked whether BCL2L12 could mediate the oncogenic effects of EYA1 on glioma development." (PMID 39897043, 2025). "We also describe a signaling pathway where EYA1 regulates BCL2L12 turnover by dephosphorylating T33, which contributes to glioma development." (PMID 39897043, 2025). "To evaluate the clinical relevance of EYA1 and BCL2L12 in glioma, we investigated their expression using immunohistochemical (IHC) staining on a glioma tissue microarray (TMA)." (PMID 39897043, 2025). "Taken together, these results demonstrate that EYA1 colocalizes and physically interacts with BCL2L12 in glioma cells." (PMID 39897043, 2025). "The signaling transduction proposed in this study is consistent with the oncogenic roles of EYA1 and BCL2L12 in glioma development as previously reported." (PMID 39897043, 2025). "Pearson correlation analysis showed a positive correlation between EYA1 and BCL2L12 proteins in glioma patient samples." (PMID 39897043, 2025). "Given that c-Myc is a known EYA1 substrate in other biological contexts, and BCL2L12 is an essential oncoprotein in glioma development, we decided to focus our further investigations on BCL2L12." (PMID 39897043, 2025). "Our study reveals that EYA1 controls the turnover of BCL2L12 by regulating BCL2L12 dephosphorylation and stabilization, implicating EYA1 as a potential therapeutic target for glioma treatment." (PMID 39897043, 2025). "Next, we investigated the biochemical interaction between EYA1 and BCL2L12 in mammalian cells and its potential impact on glioma development." (PMID 39897043, 2025). "Among these 4 proteins, SNX1 and IGHG1 were up-regulated in gliomas, while, PQBP1 and EYA1 were down-regulated in gliomas." (PMID 26370624, 2015). "Moreover, the protein expression level of EYA1 and BCL2L12 is positively correlated in glioma patient samples, suggesting that this positive regulatory relevance between EYA1 and BCL2L12 is also important in clinical settings." (PMID 39897043, 2025). "Furthermore, we validated the regulatory relationship between EYA1 and BCL2L12 in glioma by examining protein expression in patient samples." (PMID 39897043, 2025). "Moreover, we validate a positive correlation between EYA1 and BCL2L12 protein levels in glioma patient samples." (PMID 39897043, 2025). "Our analysis revealed that EYA1 was remarkably overexpressed in glioma malignant cells, unlike in other cell types and cancers." (PMID 39897043, 2025). "However, there were no common proteins which were differentially expressed in Grade II and IV with the exception of 4 proteins, SNX1, EYA1, PQBP1, and IGHG1, which were dysregulated across all the grades of gliomas." (PMID 26370624, 2015).
hepatocellular carcinoma (2 papers, 2021 to 2023). A malignant tumor that arises from hepatocytes. "LINC00511 interacts with EYA1 to promote the development of hepatocellular carcinoma via mediating miR‐195, which can be treated as a therapeutic biomarker for hepatocellular carcinoma diagnosis and treatment." (PMID 34427967, 2021).
hypospadias (2 papers, 2019). Hypospadias is the displacement of the urethral meatus on the ventrum of the penis. "Although we did not include all possible proteins encoded by hypospadias risk associated genes (for example IRX5, IRX6, EYA1) for PPIs, our investigations indicated that disruption of SP1 and SP7 activity is associated with multiple known hypospadias risk associated genes in human via PPIs." (PMID 31856834, 2019).
leukemia (2 papers, 2015 to 2016). A malignant (clonal) hematologic disorder, involving hematopoietic stem cells and characterized by the presence of primitive or atypical myeloid or lymphoid cells in the bone marrow and the blood. "Of note, SIX1 and EYA1 are targets of the onco-fusiongene MLL-ENL in leukemia, highlighting their role in hematopoietic malignancies." (PMID 26473286, 2015).